MT1P3 (metallothionein 1 pseudogene 3)
Synonyms: dJ614O4.6; C20orf127; MTL4
Gene: Processed pseudogene on chromosome 20 (35,218,009 to 35,218,185, forward strand). Ensembl gene ENSG00000229230.
Diseases named in the same sentence as MT1P3 in open-access papers:
MT1P3 is named in the same sentence as 2 diseases in open-access papers, as found by Europe PMC text mining. Sharing a sentence is not in itself a finding about the gene and the disease. The quoted sentences say what the papers report.
diabetes (1 paper, 2022). "Knockdown of lncRNA metallothionein 1 pseudogene 3 (MT1P3) can inhibit platelet activation and aggregation in an animal model of diabetes by reducing P2Y12 expression." (PMID 35883699, 2022).
type 2 diabetes (1 paper, 2020). "In this context, the non-coding Metallothionein 1 Pseudogene 3 (MT1P3) was found to be significantly upregulated in MKs from type 2 diabetes patients compared to healthy controls and, most importantly, had an impact on platelet activation and expression of the P2Y12 by sponging miR-126." (PMID 33076269, 2020).